MEF2A (myocyte enhancer factor 2A)
Description:
Transcriptional activator which binds specifically to the MEF2 element, 5'-YTA[AT](4)TAR-3', found in numerous muscle-specific genes. Also involved in the activation of numerous growth factor- and stress-induced genes. Mediates cellular functions not only in skeletal and cardiac muscle development, but also in neuronal differentiation and survival. Plays diverse roles in the control of cell growth, survival and apoptosis via p38 MAPK signaling in muscle-specific and/or growth factor-related transcription. In cerebellar granule neurons, phosphorylated and sumoylated MEF2A represses transcription of NUR77 promoting synaptic differentiation. Associates with chromatin to the ZNF16 promoter.
Synonyms: MEF2; RSRFC4; RSRFC9; ADCAD1
Tractability: Small molecule: a structure with a bound ligand is known. PROTAC: UniProt records ubiquitination sites on it; ubiquitination databases record sites on it; its protein half-life has been measured.
Gene: Protein-coding gene on chromosome 15 (99,565,404 to 99,716,488, forward strand). Ensembl gene ENSG00000068305.
Subcellular location: Nucleus
Subcellular location (Human Protein Atlas): Nucleoplasm; Cytosol
Pathways (Reactome):
Developmental Biology: Myogenesis
Signal Transduction: ERK/MAPK targets
Gene Ontology:
Molecular function: chromatin binding; DNA-binding transcription activator activity, RNA polymerase II-specific; DNA-binding transcription factor activity; DNA-binding transcription factor activity, RNA polymerase II-specific; DNA-binding transcription factor binding; histone acetyltransferase binding; histone deacetylase binding; protein binding; protein heterodimerization activity; RNA polymerase II cis-regulatory region sequence-specific DNA binding; RNA polymerase II transcription regulatory region sequence-specific DNA binding; RNA polymerase II-specific DNA-binding transcription factor binding; sequence-specific DNA binding; SMAD binding; DNA binding; protein dimerization activity; protein kinase binding
Biological process: cellular response to calcium ion; DNA-templated transcription; heart development; negative regulation of transcription by RNA polymerase II; positive regulation of cardiac muscle hypertrophy; positive regulation of transcription by RNA polymerase II; cell differentiation; dendrite morphogenesis; muscle cell development; muscle organ development; animal organ development; positive regulation of gene expression
Cellular component: nucleoplasm; nucleus; transcription regulator complex; chromatin
Genetic constraint (gnomAD): Loss-of-function variants: 25 observed, 45.81 expected, observed/expected ratio (o/e) 0.55, 90% interval 0.4 to 0.76. The upper end of that interval is the gene's LOEUF score, 0.76, which puts it in group 3 of 6, group 1 being the genes least tolerant of losing a copy. Missense variants: 511 observed, 594.56 expected, observed/expected ratio (o/e) 0.86, 90% interval 0.8 to 0.93. Synonymous variants: 231 observed, 216.42 expected, observed/expected ratio (o/e) 1.07, 90% interval 0.96 to 1.19.
Homologues: Orthologues: macaque MEF2A (99% identical), guinea pig MEF2A (97% identical), chimpanzee MEF2A (93% identical), dog MEF2A (93% identical), rabbit MEF2A (91% identical), pig MEF2A (90% identical), rat Mef2a (90% identical), mouse Mef2a (88% identical), tropical clawed frog mef2a (79% identical), zebrafish mef2aa (72% identical). Paralogues in human: MEF2C (59% identical), MEF2D (57% identical), MEF2B (30% identical), SRF (17% identical).
Diseases named in the same sentence as MEF2A in open-access papers:
MEF2A is named in the same sentence as 105 diseases in open-access papers, as found by Europe PMC text mining. Sharing a sentence is not in itself a finding about the gene and the disease. The quoted sentences say what the papers report.
cardiac hypertrophy (27 papers, 2009 to 2025). "Specifically, scGO pinpointed MEF2A, a recognized TF implicated in the development of cardiac hypertrophy." (PMID 39820437, 2024). "Acetylated H3K9 on the promoter of MEF2A, a cardiac hypertrophy‐related transcriptional regulator, caused overexpression of cardiac hypertrophy‐related genes, eventually inducing the development of cardiac hypertrophy." (PMID 30712293, 2019). "MEF-2A is also implicated in cardiac hypertrophy and myopathy due to arsenic exposure in rats." (PMID 31105874, 2019). "Myocytes specific enhancer factor 2A (MEF2A) is a target gene of miR-19a-3p and is highly expressed in cardiac hypertrophy while miR-19a-3p has low expression." (PMID 38420190, 2024). "We took advantage of this well characterized model of cardiac hypertrophy to assess the role of MEF2A and STAT3 in this cellular process since both proteins have been previously independently implicated in cardiac hypertrophy." (PMID 37019881, 2023). "The long noncoding RNA Ahit prevents myocardial hypertrophy by down-regulating MEF2A expression in synergy with SUZ12." (PMID 37008050, 2023). "Ahit serves as a scaffold to guide the SUZ12 to the promoter of MEF2A (a critical inducer of cardiac hypertrophy), leading to repressive H3K27me3 and decline in MEF2A expression." (PMID 35990951, 2022). "Many studies have shown that the cardiac nuclear transcription factor MEF2A is a critical regulator of pathological cardiac hypertrophy." (PMID 34914791, 2021). "Ahit suppresses cardiac hypertrophy through binding with SUZ12 to regulate PRC2 occupancy on the MEF2A (myocyte enhancer factor 2A) promoter." (PMID 34604357, 2021). "Both in vivo and in vitro experiments confirmed that Ahit binds and recruited SUZ12, the core protein of PRC2, to the promoter of MEF2A, acting as a scaffold and initiates H3K27me3 to mediate the downregulation of MEF2A, thereby regulating cardiac hypertrophy." (PMID 34604208, 2021). "Downregulating the expression of MEF2A and preventing cardiac hypertrophy through epigenomic modulation." (PMID 34604208, 2021). "LncRNA‐Ahit is a neighbouring gene of MEF2A, which regulate chromatin remodelling via direct binding with SUZ12 (suppressor of zeste 12) and recruiting PRC2 to promote of H3K27me3 on the MEF2A promoter region, resulting against cardiac hypertrophy." (PMID 32896990, 2020). "To MEF2A on cardiac hypertrophy‐related downstream genes in TAC mice, we assayed the regulatory relationship between MEF2A and downstream cardiac hypertrophy‐linked genes (ANP and β‐MHC)." (PMID 30712293, 2019). "MEF2A is a critical transcription factor that is involved in heart development, cardiac hypertrophy and many other cardiovascular diseases." (PMID 30712293, 2019). "Mechanistically, NCoR1 interacted with MEF2a and cooperated with class IIa HDACs to control cardiac hypertrophy." (PMID 31532577, 2019). "Another study suggests that glycogen synthase kinase3β (GSK3β), a suppressor of both myogenesis and cardiac hypertrophy, is a transcriptional target of MEF-2A." (PMID 31105874, 2019). "The findings support strategies targeting the NCoR1/MEF2a/HDACs complex in cardiomyocytes as potential novel approaches for the intervention of cardiac hypertrophy." (PMID 31532577, 2019). "MEF2A is inhibited by miR-19a-3p under physiological conditions, and during the myocardial hypertrophy process as well." (PMID 29549288, 2018). "Myocytes specific enhancer factor 2A (MEF2A), a critical executioner of cardiac hypertrophy, was predicted as a putative target of miR-19a-3p." (PMID 29549288, 2018). "Activations of the MEF2 family members (MEF2A, 2B, 2C and 2D) of transcription factors play important roles in the regulation of cardiac hypertrophy and remodeling." (PMID 29190899, 2017). "The activation of the members of the myocyte enhancer factor-2 family (MEF2A, B, C and D) of transcription factors promotes cardiac hypertrophy and failure." (PMID 20041152, 2009).
cardiac hypertrophy (continued). "A study found that REV-ERBα, upon co-localization with MEF2a and MEF2c, could specifically inhibit MEF2a/MEF2c-driven cardiac hypertrophy and the aberrant activation of gene programs in HF, thereby playing a critical role in preventing ventricular remodeling." (PMID 40255337, 2025). "MEF2a and MEF2c are key regulators of the cardiac hypertrophy gene program." (PMID 40255337, 2025). "In particular, we have documented an interaction between MEF2A and STAT3 that may balance the regulation of critical gene networks associated with the inflammatory response, cardiomyocyte cell survival and cardiac hypertrophy." (PMID 37019881, 2023). "Ventricular hypertrophy in rats exposed to arsenic trioxide may be related to the up-regulation of MEF2A, CAMKK2, CALM3 and TNNI3 in cardiomyocytes induced by this agent." (PMID 37008050, 2023). "Some evidence suggests that MEF2A is a critical factor in pathological cardiac hypertrophy." (PMID 34914791, 2021). "Moreover, we demonstrated that both SP600125 and AA attenuate the overexpression of cardiac hypertrophy-related genes (MEF2A, ANP, BNP, and β-MHC), preventing cardiomyocyte hypertrophy and dysfunction." (PMID 34914791, 2021). "Cardiac overexpression of Mef2a and Mef2c also induced cardiac hypertrophy and dilation." (PMID 34208388, 2021). "A new report revealed that SUZ12 (Suppressor of Zeste 12 Protein Homolog) could mediate the downregulation of myocyte enhancer factor 2A, thereby preventing cardiac hypertrophy." (PMID 32620106, 2020). "MEF2a, MEF2c, and MEF2d have been demonstrated to play vital roles in cardiac hypertrophy." (PMID 31532577, 2019). "Furthermore, MEF2a, MEF2c, and MEF2d are well characterized for their crucial roles in cardiac hypertrophy, and MEF2b has been implicated to play a role in cardiac development." (PMID 31532577, 2019). "However, another study showed that MEF2A overexpression is sufficient to induce cardiac hypertrophy, and dominant negative inhibition of MEF2A signaling blocked cardiomyocyte hypertrophy." (PMID 27105518, 2016). "However, the relationship between HDAC5, ERK/EGR1 signaling, and MEF2A in the context of cardiac hypertrophy remains unclear." (PMID 37667300, 2023). "In addition, ChIP-PCR showed that MEF2A could bind to the promoters of cardiac hypertrophy biomarker genes such as ANP, BNP, and β-MHC, suggesting its role in the transcriptional regulation of these genes." (PMID 34914791, 2021). "SFI can upregulate the expression of miR-19a-3p, and downregulate the expression of MEF2A and β-myosin heavy chain (β-MHC), so attenuate cardiac hypertrophy." (PMID 38420190, 2024). "Activation and elevated expression of MEF2A and MEF2C in the adult heart is often closely related to myocardial hypertrophy." (PMID 37008050, 2023). "Furthermore, lower-expression of miR-19a-3p may enhance the expression of MEF2A, β-MHC, BNP and TRPC1 in cardiomyocyte hypertrophy, which seemingly implies that lower-expression of miR-19a-3p mediated MEF2 signaling might be a cause of myocardial hypertrophy." (PMID 29549288, 2018). "In the present study, ANP, MEF2A and MEF2C (molecular markers of cardiac hypertrophy) gene expressions were significantly higher in the diabetic group compared with the controls." (PMID 23497378, 2013). "Furthermore, our findings suggest that HDAC5 may regulate MEF2A expression through the ERK/EGR1 signaling pathway, contributing to the progression of myocardial hypertrophy." (PMID 37667300, 2023).
coronary artery disease (16 papers, 2011 to 2024). "MEF-2A mutations is associated with premature myocardial infarction and coronary heart disease.Also associated with reduced myofibroblast proliferation and differentiation." (PMID 31105874, 2019). "Since then, researchers have conducted a large number of studies on the relationship between the genetic polymorphism of MEF2A and coronary heart disease, but the findings are controversial." (PMID 31182679, 2019). "Here, we studied the effects of MEF2A on the senescent phenotype of vascular endothelial cells (VEC) and downstream signaling pathway, and the association between plasma MEF2A levels and coronary artery disease (CAD)." (PMID 31182679, 2019). "A mutation of MEF2A was also reported in an inherited disorder with features of coronary artery disease, suggesting its participation in endothelial function." (PMID 24797675, 2014). "Mutations in MEF2A have been associated with with coronary artery disease (CAD), however, further evidence suggests that this is not a common cause of CAD among whites." (PMID 23046476, 2012). "Several SNPs, which have been associated with hypertrophic cardiomyopathy and coronary artery disease, were identified in the human MEF2A gene." (PMID 22714905, 2012). "Beyond the 21-bp deletion, point mutations in exon 6 and 7 were reported to be associated with an increased risk of myocardial infarction, further implicating the association of MEF2A with coronary disease, and one of these point mutations, Pro297Leu, was independently replicated." (PMID 24106602, 2013). "MEF2A has also been implicated as a candidate gene for coronary artery disease, and our results suggest that MEF2A dysregulation might be involved in smooth muscle cell apoptosis in the ruptured sIA walls." (PMID 21592412, 2011). "Since then, many researchers have extensively studied the correlation between MEF2A genetic variation and coronary artery disease (CAD)." (PMID 31182679, 2019). "Contrasting mutational and functional analysis of MEF-2A have been reported in many studies which identify MEF-2A as a susceptibility gene for premature myocardial infarction and coronary artery disease (CAD)." (PMID 31105874, 2019). "Of the down-regulated genes, 32 were regulated by myocyte enhancer factor 2A (MEF2A), a transcription factor implicated in coronary artery disease (p = 3.5 × 10−7)." (PMID 25881171, 2015). "Moreover, Mef2A has been recognized for its ability to delay endothelial senescence and, consequently, is considered a potential plasma biomarker for predicting coronary artery diseases in the elderly." (PMID 39180980, 2024). "The genetic variation of MEF2A gene does not explain the risk of coronary heart disease in most people." (PMID 35047575, 2021). "In fact, the MEF2A gene (OMIM 600660) encodes for a protein that maintains the appropriate mitochondrial content and the cytoarchitectural integrity in the postnatal heart in mice and seems to be responsible for cardiac abnormalities (coronary artery disease and myocardial infarction) in humans." (PMID 28899882, 2017).
diabetes (10 papers, 2013 to 2025). "In the diabetes model of insulin deficiency induced by streptozotocin, the expression of Mef2a in heart and skeletal muscle decreases significantly." (PMID 37008050, 2023). "CAD was used as a dependent variable, whereas age, gender, smoking, diabetes, MEF2A, total cholesterol, HDL-C, LDL-C, and CK-MB were included as covariates." (PMID 31182679, 2019). "We found that Diabetes mellitus increased cardiac MEF2A expression, aggravated cardiac dysfunction and myocardial fibrosis through the accumulation of fibroblasts via EndMT." (PMID 27105518, 2016). "We conclude that inhibition of endothelial cell-derived MEF2A might be beneficial in the prevention of diabetes mellitus-induced cardiac fibrosis by partially inhibiting EndMT through interaction with p38MAPK and Smad2." (PMID 27105518, 2016). "Our results indicated that elevated levels of MEF2A may be a trigger of hyperglycemia-induced EndMT and as a profibrotic factor in diabetes-induced cardiomyopathy." (PMID 27105518, 2016). "Thus, prolonged activation of MEF2A-dependent genes in myocytes may become maladaptive, contributing to pathological remodeling and accumulation of focal fibrosis in diabetes-induced cardiomyopathy." (PMID 27105518, 2016). "The expressions of genes such as glucose transporter protein 4 (GLUT4), myocyte enhancer factor-2 (MEF-2A), and nuclear respiratory factor-1 (NRF-1) were investigated in a palmitate-induced C2C12 cell model of type 2 diabetes mellitus." (PMID 40869081, 2025). "We induced type 1 diabetes mellitus using the toxin streptozotocin (STZ) in mice and injected with lentivirus-mediated short-hairpin RNA (shRNA) in myocardium to inhibit MEF2A expression." (PMID 27105518, 2016). "Diabetes upregulated the expression of ANP, MEF2A, MEF2C and p300." (PMID 23497378, 2013). "To determine whether this applies to our CMECs and whether the observed dysregulation of KLF expression in diabetes is linked to the observed MEF2D dysregulation in our diabetic models, we knocked down MEF2A or MEF2D in nondiabetic HCMECs and analyzed KLF2 and KLF4 gene expression." (PMID 36768805, 2023).
myocardial infarction (10 papers, 2006 to 2024). Gross necrosis of the myocardium, as a result of interruption of the blood supply to the area, as in coronary thrombosis. "A deletion mutation in MEF2A was identified in a large pedigree with an autosomal dominant inheritance pattern of myocardial infarction (MI) and CAD." (PMID 24106602, 2013). "Third, two other transcription factors have been implicated in cardiovascular phenotypes, MEF2A (myocardial infarction) and USF1 (lipid traits)." (PMID 16934006, 2006). "A number of markers, such as myeloid-related protein 14 (MRP-14), cyclooxygenase-1 (COX-1), 5-lipoxygenase activating protein (FLAP), leukotriene A4 hydrolase (LTA4H) and myocyte enhancing factor 2A (MEF2A), have been linked to acute coronary syndromes, including myocardial infarction." (PMID 19578513, 2008). "Known variants in dominant non-ACMG genes were mostly present in one participant, except for the missense Pro279Leu variant in the MEF2A gene (rs121918529) observed in three participants and associated with CAD/myocardial infarction." (PMID 34691145, 2021).
atherosclerosis (9 papers, 2013 to 2023). A disease characterized by the build-up of fatty material and calcium deposition in the arterial wall resulting in partial or complete occlusion of the arterial lumen. "The inflammation patterns of apolipoprotein E-deficient mice following the knockdown of MEF-2A showed accelerated atherosclerosis." (PMID 31105874, 2019). "In apoE-deficient mice, MEF2A inhibition accelerates atherosclerosis." (PMID 31182679, 2019). "Evidence for the protective effect of MEF2A on blood vessels also includes the observation that inhibition of MEF2A in ApoE-/- mice promotes a vascular inflammatory response and atherosclerosis." (PMID 37008050, 2023). "MEF-2A is involved in the pathogenesis of HTLV-1 and ATLL.Accelerates the progression of atherosclerosis.Implicated in HCC and gastric cancer." (PMID 31105874, 2019). "In the present study, we investigated the progression of atherosclerosis by examining inflammation in apolipoprotein E-deficient mice (APOE KO) following delivering MEF2A shRNA and found that silencing MEF 2A accelerates atherosclerosis." (PMID 25793529, 2015). "Resveratrol was failure to restore or promote the expression of MEF2A silenced by siRNA in vascular endothelial cells, which might be the major reason for that resveratrol lost its protection against atherosclerosis in MEF2A-silenced apoE−/− mice." (PMID 35047575, 2021). "The identified atherosclerosis-associated candidate genes include lipoprotein receptor-related protein 6 (LRP6) at 12q13.2, arachidonate 5-lipoxygenase-activating protein (ALOX5AP) at 13q12-13, and myocyte enhancer factor 2A (MEF2A) at 15q26.3." (PMID 32197550, 2020). "The findings that MEF2A inhibition induced VEC senescence may explain to some extent the molecular mechanism of MEF2A knockdown to accelerate atherosclerosis." (PMID 31182679, 2019).